UBXN2A (UBX domain protein 2A)
Diseases named in the same sentence as UBXN2A in open-access papers:
UBXN2A is named in the same sentence as 9 diseases in open-access papers, as found by Europe PMC text mining. Sharing a sentence is not in itself a finding about the gene and the disease. The quoted sentences say what the papers report.
colon cancer (6 papers, 2015 to 2024). "This study utilizes in vitro and in vivo approaches to reveal that VTD-dependent induction of UBXN2A can target the Rictor-mTORC2 pathway in human colon cancer." (PMID 39502780, 2024). "The level of UBXN2A protein in colon tumour tissues is markedly lower than that in adjacent normal tissues." (PMID 38365777, 2024). "VTD-dependent expression of UBXN2A leads to the deactivation of mortalin in colon cancer cells, making VTD a potential targeted therapy in malignant tumors with high levels of mortalin." (PMID 35347121, 2022). "A high-throughput drug screen revealed that veratridine (VTD), a natural plant alkaloid, induces expression of the anti-cancer protein UBXN2A in colon cancer cells." (PMID 35347121, 2022). "The molecular events behind the dual function of UBXN2A in apoptosis and in modulating the epithelial–mesenchymal transition in colon cancer cells are currently under investigation in our group." (PMID 30107089, 2018). "In sum, the results from our study demonstrate that UBXN2A appears to exert antiproliferation and pro‐apoptosis as well as antimigration effects in colon cancer cells." (PMID 30107089, 2018). "As previously shown, we first reconfirmed that VTD enhances expression of UBXN2A in a dose‐dependent manner in LoVo, a well‐differentiated colon cancer cell line." (PMID 30107089, 2018). "As previously shown in HEK293 and differentiated PC12 cells, we were able to show that UBXN2A is co‐immunoprecipitated with the CHIP E3 ubiquitin ligase in HCT‐116 colon cancer cells." (PMID 30107089, 2018). "UBXN2A is dominantly localized in the nucleus in colon cancer cell lines and translocates to cytoplasmic compartments upon genotoxic stress, where it binds to mot-2 protein." (PMID 27754413, 2016). "A proteomic approach for identifying cellular proteins interacting with UBXN2A in a HCT116 colon cancer cell line revealed UBXN2A binds to mortalin-2 (GRP75, HSPA9, mot-2) protein." (PMID 27754413, 2016). "Despite its anti-cancer role, we observed that 50% of patients with colon cancer have underexpressed UBXN2A in their tumors, while at the same time 75% of these patients have an overexpression of mot-2." (PMID 26188124, 2015). "Cell-based assays coupled with gene-specific shRNA silencing confirmed that VTD was sufficient to induce UBXN2A protein levels, resulting in colon cancer cell death in UBXN2A- and mot-2-dependent manners." (PMID 26188124, 2015). "Here, we identify and establish UBXN2A as a colon tumor suppressor in both in vitro and in vivo models." (PMID 26188124, 2015). "Overall, these results indicate plant alkaloid Veratrine can selectively increase protein level of UBXN2A in HCT-116 colon cancer cells." (PMID 26188124, 2015). "To answer this question, we examined apoptosis and cell death markers in UBXN2A-induced cells treated with 5-FU, a thymidylate synthase inhibitor commonly used in patients with colon cancer." (PMID 26188124, 2015). "Further analysis employing a higher number of patients with colon cancer is needed to determine the relation of UBXN2A protein levels and patient survival in different stages." (PMID 26188124, 2015). "LoVo colon cancer cells stably expressing shRNA against UBXN2A (clones 5 and 6) were treated with VTD (30 and 100 μM) followed by WB." (PMID 26188124, 2015). "We have shown that elevated UBXN2A can suppress colon cancer cell migration." (PMID 39502780, 2024). "We hypothesized that elevated UBXN2A in the presence of VTD suppresses colon cancer migration and invasion." (PMID 39502780, 2024). "UBXN2A suppresses the stemness of colon cancer cells dominantly through the Rictor-mTORC2 pathway." (PMID 39502780, 2024).
colon cancer (continued). "While UBXN2A overexpression decreases mot‐2 protein levels through the ubiquitin–proteasome pathway, mot‐2 can be upregulated transcriptionally in response to genotoxic stress in colon cancer cells induced by 5‐FU treatment." (PMID 30107089, 2018). "We decided to determine whether VTD‐dependent overexpression of UBXN2A leads to downregulation of mot‐2 proteins in colon cancer cells." (PMID 30107089, 2018). "Finally, establishing VTD, a UBXN2A enhancer molecule, as an antimigration agent will set up a unique platform for new preclinical drug development in colon cancer research." (PMID 30107089, 2018). "To verify whether UBXN2A can target mot‐2 in colon tissues for proteasomal degradation similar to colon cancer cells, we prepared tissue homogenates of proximal and distal colon from C57Bl/6 mice." (PMID 30107089, 2018). "The VTD-dependent expression of UBXN2A is a potential candidate for designing novel strategies for colon cancer treatment because: 1) In 50% of colon cancer patients, UBXN2A protein levels in tumor tissues are significantly lower than those in the adjacent normal tissues." (PMID 26188124, 2015). "Furthermore, WB of 48 human tumor and adjacent normal tissue lysates verified a marked downregulation of UBXN2A in ∼50% of patients with colon cancer." (PMID 26188124, 2015). "Ongoing experiments in our laboratory are using truncated and mutant forms of UBXN2A and CHIP proteins to enhance our understanding of UBXN2A/CHIP functions in cancer cells and mouse models of colon cancer." (PMID 30107089, 2018). "To further confirm the UBXN2A‐dependent reduction in mot‐2 proteins in cancer cells, we used a Tet‐on system to induce the expression of UBXN2A in HCT‐116 colon cancer cells." (PMID 30107089, 2018). "Despite a reasonable induction of UBXN2A by VTD in HCT-116, we did obtain a modest effect in HCT-116 poorly differentiated colon cancer cells." (PMID 26188124, 2015). "However, UBXN2A-dependent inhibition of mortalin in the presence of a safe and tolerable dose of VTD offers a colon cancer-specific treatment option." (PMID 35347121, 2022). "To identify whether the UBXN2A/CHIP complex targets mot‐2 in tumor tissues, we decided to examine the presence of the UBXN2A/CHIP/mot‐2 complex in a mouse model of colon cancer." (PMID 30107089, 2018). "Measurement of UBXN2A in cells and tissues confirmed UBXN2A expression increases at least 1.84-fold in colon tissues (1.32-fold in small intestine and no changes in liver) in the presence of Veratrine and is increased 2–4 fold by its purified form, VTD, in HCT-116 colon cancer cells." (PMID 26188124, 2015). "Interestingly, these data suggested that UBXN2A changes may have a correlation with the stages of colon cancer, as several patients at stage III had a low level of UBXN2A (inset)." (PMID 26188124, 2015).
adenoma (1 paper, 2018). A neoplasm arising from the epithelium. "Our ongoing investigation will reveal how UBXN2A, CHIP, and mot‐2 cross talk in CRC patient tissues, including adenoma, adenocarcinoma, and normal intestinal tissues." (PMID 30107089, 2018).
colon adenocarcinoma (1 paper, 2015). "Analysis of the Oncomine database revealed that UBXN2A expression is downregulated in some human cancers, including in patients with colon adenocarcinoma." (PMID 26188124, 2015).
metastatic tumors (1 paper, 2018). "Finally, although our study demonstrated a role for UBXN2A in negative regulation of mot‐2 via the CHIP E3 ubiquitin ligase, it is possible that the UBXN2A/CHIP complex may also negatively regulate other oncoproteins or their tumorigenic pathways activated in both primary and metastatic tumors." (PMID 30107089, 2018).
osteosarcoma (1 paper, 2018). A usually aggressive malignant bone-forming mesenchymal neoplasm, predominantly affecting adolescents and young adults. "In a set of parallel experiments, we used U2OS osteosarcoma cells stably expressing shRNA against UBXN2A (clones 2 and 3) or scramble shRNA." (PMID 30107089, 2018).
cancer (9 papers, 2015 to 2025). A tumor composed of atypical neoplastic, often pleomorphic cells that invade other tissues. "Further studies are required to dissect the various mechanisms underlying UBXN2A anti-cancer functions upon its binding to mortalin and how UBXN2A-dependent inhibition of the mortalin oncoprotein pathway can alter the apoptotic efficacy of chemotherapy." (PMID 27754413, 2016). "The ability of VTD to induce UBXN2A expression, causing significant cancer cell death alongside standard chemotherapy, suggests VTD could be a potential complementary strategy in the treatment of solid tumors with high levels of mot-2." (PMID 26188124, 2015). "We completed invasion assays to justify further that VTD functions as a potent anti-cancer molecule by targeting the overactivated mTORC2 pathway by the UBXN2A-Rictor axis." (PMID 39502780, 2024). "This dual targeting function of both the apoptotic and AKT pathways is mediated through the UBXN2A-Rictor axis, generating a progressive apoptotic cascade in cancer cells." (PMID 39502780, 2024). "In this study, we confirm that VTD-dependent expression of UBXN2A induces apoptosis in cancer cells, effectively exploiting a major anti-cancer mechanism with a small molecule." (PMID 35347121, 2022). "Using western blotting (WB), flow cytometry, and immunocytochemistry, we show that UBXN2A is required for efficient ubiquitination and degradation of mot‐2 proteins in cancer cell lines and in mouse colon tissues." (PMID 30107089, 2018). "Together, these results indicate that VTD can decrease the protein levels of mot‐2 via upregulation of UBXN2A in a dose‐dependent manner in diverse cancer types." (PMID 30107089, 2018). "Silencing UBXN2A in cancer cells with shRNA or haploinsufficiency of UBXN2A expression in UBXN2A+/− mice resulted in an elevation of mot‐2 protein." (PMID 30107089, 2018). "These actions of UBXN2A in cancer cells are likely mediated through mot‐2 signaling pathways, while we cannot eliminate mot‐2 independent pathways." (PMID 30107089, 2018). "Selective destabilization of mot‐2 protein by UBXN2A leads to inhibition of cell proliferation and decreased cancer cell migration." (PMID 30107089, 2018). "Pharmacological upregulation of UBXN2A in cancer cells by VTD led to downregulation of mot‐2 in diverse cancer cell lines." (PMID 30107089, 2018). "Induction of UBXN2A promotes ubiquitination and proteasomal degradation of mot‐2 in cancer cell lines in a CHIP‐dependent manner." (PMID 30107089, 2018). "Together, this set of experiments further confirmed UBXN2A can play a critical role in anti-cancer mechanism of VTD in cancer cells." (PMID 26188124, 2015). "This study establishes the concept that the anti-cancer protein UBXN2A plays a crucial opposite role in colon tumorigenesis, and it justifies the transition of a novel plant alkaloid compound to clinical development." (PMID 26188124, 2015). "Future studies, including ongoing projects in our group, will determine whether UBXN2A-dependent degradation of mortalin alters the fate of mortalin protein partners and improves cancer cell response to traditional anti-cancer therapies." (PMID 36819105, 2023). "A systematic analysis of apoptotic elements and their regulatory factors will be essential to determining the underlying mechanisms behind this cross‐resistance, which occurs following initial apoptotic events and cell death regulated by UBXN2A in cancer cells." (PMID 30107089, 2018). "In addition, overexpression or silencing of UBXN2A increases response to conventional chemotherapy in cancer cells with enriched mot-2." (PMID 27754413, 2016). "VTD-treated cancer cells undergo cell death in UBXN2A- and mot-2-dependent manners." (PMID 26188124, 2015).
cancer (continued). "Depletion of CD44 positive stem cancer cells in the presence of VTD suggests this alkaloid may target a sub-population of cancer stem cells through the UBXN2A-mot-2 pathway as described for other natural products." (PMID 26188124, 2015). "Therefore, it will be very interesting to further explore whether UBXN2A can reverse cancer cell growth and invasiveness in tumors with a low level of CHIP." (PMID 30107089, 2018). "This study explored the anti-cancer mechanisms and therapeutic efficacy of a mTORC2 specific potent anti-cancer molecule, VTD, as a plant alkaloid-based UBXN2A enhancer." (PMID 39502780, 2024). "For example, most cancer tissues exhibit weak to moderate cytoplasmic and/or nuclear immunoreactivity in the ASPSCR1, UBXN2A, UBXN10, UBXN1, FAF1, FAF2, UBXD2B proteins." (PMID 38365777, 2024). "UBXN2A suppresses mortalin, a heat shock protein, with dominant roles in cancer development including epithelial–mesenchymal transition (EMT), cancer cell stemness, drug resistance, and apoptosis." (PMID 35347121, 2022). "Pharmacological upregulation of UBXN2A using a small molecule, veratridine (VTD), decreases the level of mot‐2 in cancer cells." (PMID 30107089, 2018). "As it has been reported for other anti-cancer proteins such as SP1, UBXN2A's up- and down-regulation can coordinate with the stage of cancers." (PMID 26188124, 2015). "This novel protein complex (UBXN2A-mot-2) exists only in the cytoplasm of cancer cells and not in normal cells due to the dominant mitochondrial localization of mot-2 in normal cells." (PMID 26188124, 2015).
tumor (8 papers, 2015 to 2025). "The tumor growth rate was insignificant between UBXN2A (+/−) and WT at the pre-treatment ultrasound stage." (PMID 39502780, 2024). "More importantly, VTD (0.1 mg/kg) decreased tumor growth in the UBXN2A (+/−) mice (green) despite having half the amount of UBXN2A as their WT counterparts." (PMID 39502780, 2024). "An in vivo study showed a 50% reduction in tumor size in a xenograft mouse model treated with UBXN2A." (PMID 39456564, 2024). "It has been shown to possess anti-tumor activity mediated by the selective enhancement of the transcription of UBXN2A, a binding partner and inhibitor of Mortalin." (PMID 39456564, 2024). "A CRC mouse model that mimics the natural stages of human sporadic CRC revealed that VTD treatment significantly decreases tumor growth in a UBXN2A-dependent manner." (PMID 39502780, 2024). "Experiments in UBXN2A haploinsufficient mice revealed that the enrichment of UBXN2A by VTD in a time-dependent manner slows the tumor formation in the lower colon and rectum." (PMID 39502780, 2024). "Enhancement of UBXN2A leads to apoptosis at the cellular level and in living animals, thereby inhibiting tumour growth, reproduction, and metastasis." (PMID 38365777, 2024). "In an advanced-staged tumor response approach, we confirmed that induction of UBXN2A can lead to more apoptotic/necrotic events during the development of stablished tumors using PSVue 794, a distinct marker of apoptosis/necrosis used in live mice." (PMID 26188124, 2015). "In summary, successful tumor growth suppression of xenografts in the presence of induced UBXN2A led to a drug screen to identify a natural compound capable of upregulating UBXN2A protein in both in vitro and in vivo models." (PMID 26188124, 2015). "We next examined how induction of UBXN2A contributes to tumor suppression in xenograft mouse models." (PMID 26188124, 2015). "We showed that UBXN2A enhancement leads to apoptosis at the cellular level and in live animals, resulting in tumor growth suppression." (PMID 26188124, 2015). "Measurement of the growth rate of tumors showed that induction of UBXN2A led to a 50% reduction of tumor size and mass as well as the central necrosis in some mice 40 days after implantation." (PMID 26188124, 2015). "UBXN2A and cytoplasmic mot-2 protein levels are low in tumor tissues; thus, VTD could enhance tumor-specific toxicity, while normal cells remain intact." (PMID 35859897, 2022). "Therefore, we decided to examine whether UBXN2A prevents tumor cell migration by down‐regulating mot‐2 after initial pro‐apoptotic effects." (PMID 30107089, 2018). "Patients with high UBXN2A proteins may delay tumor progression and prolong overall survival, and patients with a low level of UBXN2A are more often found in the late stage of tumors (progressive tumor)." (PMID 26188124, 2015). "The inhibited tumor growth observed in weeks 10 and 12 in VTD (0.1 mg/kg) treated UBXN2A (+/−) mice shows that elevation of UBXN2A by VTD can overcome pre-existing low UBXN2A levels and actively slow tumor growth." (PMID 39502780, 2024). "Consistent with a tumor suppressor role, CRC tissues with worse histological grades exhibit decreased UBXN2A protein expression." (PMID 39502780, 2024). "The total tumor growth from ethanol (0.01%) treated Wild Type (WT) mice, VTD (0.1 mg/kg) treated heterozygous haploinsufficient UBXN2A (+/−) mice, and VTD (0.1 mg/kg) treated WT mice, was measured at the pre-treatment, post-treatment, and terminal stages." (PMID 39502780, 2024). "The existence of a multiprotein complex containing UBXN2A, CHIP, and mot‐2 suggests a synergistic tumor suppressor activity of UBXN2A and CHIP in mot‐2‐enriched tumors." (PMID 30107089, 2018).
UBXN2A also shares sentences with these, for which no sentence is quoted: adenocarcinoma (1 paper); colorectal tumors (1).